Y_RNA (Y RNA )
Gene: Miscellaneous RNA gene on chromosome 8 (105,929,126 to 105,929,238, reverse strand). Ensembl gene ENSG00000201627.
Homologues: Orthologues: chimpanzee Y_RNA (99% identical), macaque Y_RNA (95% identical). Paralogues in human: RNY1 (86% identical), Y_RNA (85% identical), Y_RNA (84% identical), Y_RNA (83% identical), RNY1P11 (82% identical), RNY1P8 (82% identical), Y_RNA (82% identical), Y_RNA (81% identical), RNY1P10 (80% identical), Y_RNA (80% identical), Y_RNA (79% identical), RNY1P5 (78% identical), and 97 more.